IL6 (interleukin 6)
Diseases named in the same sentence as IL6 in open-access papers (continued):
Sharing a sentence is not in itself a finding about the gene and the disease.
autoimmune myocarditis (22 papers, 2009 to 2024). Autoimmune myocarditis is an autoimmune disease that affects the heart. "PPARα inhibits activator protein −1 (AP-1)-dependent genes involved in inflammation and tumor progression and suppresses Th17 cells through modulation of IL-6/STAT3/RORγt signaling in rat models of autoimmune myocarditis." (PMID 38398835, 2024). "IL-6 KO mice that are immunized against a self-antigen (myosin heavy-chain peptide) are protected from autoimmune myocarditis as compared to wild-type mice." (PMID 34696354, 2021). "While the absence of IL-6 has been associated with increased chronic myocarditis during CVB infection, models of experimental autoimmune myocarditis have shown that IL-6 can promote autoimmune dysfunction." (PMID 34696354, 2021). "Previously, the addition of recombinant IL-6 following encephalomyocarditis virus (EMCV) infection resulted in a decrease in disease severity of autoimmune myocarditis." (PMID 19587788, 2009). "Previous results have shown that the inflammatory cytokine interleukin (IL)-6 is integral to the development of experimental-induced autoimmune myocarditis." (PMID 19587788, 2009). "Low-dose MTX has been shown to reduce levels of TNF-α and interleukin-6 (IL-6) and increase the level of IL-10 in the plasma of rats with cardiac myosin-induced autoimmune myocarditis, as well as increase left-ventricular ejection fraction and fractional shortening." (PMID 36142538, 2022). "IL-6 is crucial for Th17 differentiation through the induction of retinoic acid receptor-related orphan nuclear receptor, which is a critical event in the onset of experimental autoimmune myocarditis (EAM)." (PMID 35402550, 2022). "A recently study on autoimmune myocarditis reported PPARα may play an important role by regulating IL-6/STAT3 pathway on Th17 cell differentiation which contributes to inflammatory response." (PMID 35414769, 2022). "It had been found that anti-IL-6 treatment could reduce the proportion of Th17 cells, reducing the inflammatory reaction of autoimmune myocarditis." (PMID 30176160, 2018). "Indeed, GM-CSF is essential for IL-6 and IL-23 production by DCs during the priming phase of autoimmune myocarditis and is required for inflammatory DC development from monocytes in a model of repeated immunization with methylated BSA and CFA." (PMID 22065991, 2011). "Similarly, in a murine model of autoimmune myocarditis, GM-CSF acts during priming of Th17 responses by promoting IL-6 and IL-23 production from DCs and during ongoing autoimmune responses by promoting survival of autoreactive CD4+ T cells." (PMID 22065991, 2011). "Thus, it is valuable to decipher the role of IL-6 in the context of viral-induced autoimmune myocarditis." (PMID 19587788, 2009). "Autoimmune myocarditis persists and progressively evolves into DCM with the involvement of cardiac macrophages, fibroblasts, and cytokines, in which cytokines such as IL-1β and IL-6 promote DCM at this stage." (PMID 36827455, 2023). "Likewise, miR-590-3p was found to inhibit the p50 subunit of NFκB, thusly decreasing IL-6 and TNF-α expression in a model of experimental autoimmune myocarditis (EAM) in Lewis rats." (PMID 31671621, 2019). "In addition, the proinflammatory markers, c-fos, IL-6, iNOS, and IL-1β, were upregulated only in the hearts of male but not female rats with autoimmune myocarditis." (PMID 35754849, 2022).
cataract (22 papers, 2012 to 2025). Partial or complete opacity of the crystalline lens of one or both eyes that decreases visual acuity and eventually results in blindness. "Inverse variance weighting revealed that TIGAR decreased the risk of cataracts, whereas IL6 increased the risk of cataract." (PMID 40598458, 2025). "Elevated levels of markers such as C-reactive protein (CRP) and interleukin-6 (IL-6) have been implicated in the pathogenesis of cataracts." (PMID 38638289, 2024). "In one such study, there was an increase in nuclear sclerotic cataracts associated with increased levels of serum IL-6 in elderly human subjects." (PMID 23049540, 2012). "Similarly, the association between IL6 and the risk of cataracts was significant, with an OR of 1.871 (95% CI = 1.261–2.776, p = 0.002)." (PMID 40598458, 2025). "In addition, our MR results further confirmed that IL6 is a potential causal risk factor for cataracts." (PMID 40598458, 2025). "TIGAR and IL6 were found to be causally linked to cataracts risk." (PMID 40598458, 2025). "We evaluated the causal link between TIGAR and IL6 levels and cataracts." (PMID 40598458, 2025). "TIGAR and IL6 were identified to be causally associated with cataracts." (PMID 40598458, 2025). "In summary, based on integrated bioinformatics analysis, in vitro experimental verification, and MR analysis, we determined two ferroptosis-specific expressed genes, TIGAR and IL6, as potential biomarkers for the diagnosis and treatment of cataracts." (PMID 40598458, 2025). "We specifically selected individuals from the European population in our dataset to eliminate any confounding factors between SNPs and TIGAR, IL6, and cataracts." (PMID 40598458, 2025). "Venous blood samples from 104 cataract patients and 100 healthy subjects revealed significantly higher levels of interleukin-6 (IL-6), IL-1β, C-reactive protein (CRP) and tumor necrosis factor-1α (TNF-1α) in the cataract group than in the healthy group." (PMID 39556543, 2024). "Consequently, we speculate that individuals with elevated IL-6 levels may share a significant overlap with the aging population, which provides a potential explanation for the association between elevated IL-6 levels and an increased risk of cataracts." (PMID 38327497, 2024). "When UM patients’ aqueous humor was compared to those of subjects with cataracts, the results revealed greater amounts of IL-6, IL-8, EGF, bFGF, macrophage inhibitory factor (MIF), and MCP-1." (PMID 39596556, 2024). "Patients with cataracts exhibit notable increases in the expression levels of interleukin-6 (IL-6), IL − 1β, and tumor necrosis factor-α (TNF-α) compared to healthy individuals." (PMID 38327497, 2024). "The present study demonstrated lower concentrations of IL-6 in cataract patients (the entire group), versus the control group of healthy subjects." (PMID 37892980, 2023). "Since cataract is negatively correlated with visual functions, IL-6 released in the muscles as a result of exercise enters the blood." (PMID 37892980, 2023). "In nAMD patients, IP-10 level was significantly higher and IL-6 level was significantly lower compared with those of cataract patients as controls." (PMID 29348424, 2018). "In our study raised levels of IL-6 and IL-8 indicate an inflammatory response among the individuals with cataracts, more so among the HIV-infected individuals." (PMID 29351788, 2018). "IL-6 is usually undetectable in the vitreous of normal eyes but has been detected in aqueous in normal eyes with cataracts." (PMID 29351788, 2018). "In the cataract cases, mean (± SD) IL-6, IL-8, MCP-1, TNF-α, PDGF-AA, PDGF-AB/BB, and VEGF levels were 35.6±109.5, 6.0±9.2, 971.3±500.5, 0.9±0.4, 30.1±15.7, 1.2±3.1, and 75.3±35.0 pg/mL, respectively." (PMID 26771310, 2016).
cataract (continued). "Between Chinese patients with UM and control subjects with cataracts, significant differences were observed in the expression of numerous angiogenic, chemotactic, and inflammatory cytokines, such as IP-10, IL-6 and IL-8, NGF-β, PLGF-1, b-FGF, EGF, VEGF-A, and RANTES." (PMID 39596556, 2024). "One of the possible mechanisms is that pro-inflammatory foods can increase the effects of pro-inflammatory factors (IL-1, IL-6, TNFα) on the transcription of acute-phase proteins, which leads to increased mitosis and collagen synthesis in lens epithelial cells, triggering cataracts." (PMID 39015537, 2024). "The lower levels of IL-6, observed in the cataract patients, may also result from reduced physical activity, which has been also suggested by other authors." (PMID 37892980, 2023). "Statistically significant differences were also found between cataract and healthy males for the measurements of IL-6, resistin and adiponectin concentrations—the IL-6 and resistin concentrations were lower, and the adiponectin levels were higher in the group of cataract patients." (PMID 37892980, 2023). "The levels of IL-6 may have been influenced by adiponectin, for which serum levels were higher in cataract patients, compared to in controls." (PMID 37892980, 2023). "Likewise, the IL-6 and resistin concentrations were lower, while the concentrations of omentin-1 and adiponectin were higher, in females with cataract, relative to the levels measured in male controls." (PMID 37892980, 2023). "The IL-6 and resistin concentrations, in turn, showed higher levels in all controls, i.e., by 30% (p < 0.05) and 64.9% (p < 0.001), respectively, compared to the cataract patients." (PMID 37892980, 2023). "Inflammatory response by IL-1b and possibly IL-6 may play a role in UVR-B-induced cataracts." (PMID 34024244, 2021). "Inflammation is indeed a key factor in the development of cataracts, as evidenced by the increased levels of IL-1, IL-1β, IL-6, and TNF-alpha in the vitreous fluid of cataract patients." (PMID 39556543, 2024). "High levels of IL-6 and IL-8 have been found in the aqueous humor of patients with AMD compared to patients with cataracts, and a recent meta-analysis confirmed that the levels of IL-8 are increased in patients with wet AMD." (PMID 33920232, 2021). "In the PHA-stimulated PBMC cultures, IL-2, IFN-γ, IL-6, and IL-17A were significantly increased, and the IL-6 level was significantly higher in the VKH patients than in the BD and AR cataract patients." (PMID 25303043, 2014). "The expression levels of IL-2, IL-4, IL-6, IL-10, IL-17A, and IFN-γ were analyzed in the AqH, and PHA-stimulation and non-PHA-stimulated cultures of PBMCs from these three types of cataract patients." (PMID 25303043, 2014). "IL-6 and IFN-γ were identified above the detection limits, but, among the BD and VKH cataract patients, only the levels of IL-6 were significantly higher in both the AqH and PBMC non-PHA cultures compared with the levels observed in the AR cataract patients." (PMID 25303043, 2014). "We inferred that the expressions of IL-2, IL-4, IL-6, IL-10, IL-17A, and IFN-γ were the most likely to differ between inflammatory cataracts that are secondary to BD and VKH and AR cataracts." (PMID 25303043, 2014). "Cytokines IL-6, IL-17 and growth factor VEGF and PDGF are potent activators of STAT3, and the vitreous levels of these cytokines/growth factors were significantly higher in PDR patients compared with those in cataract patients." (PMID 31286987, 2019). "However, we observed that IL-6 was significantly elevated in both the BD and VKH patients compared with the AR cataract patients (P = 0.017 and P = 0.004, respectively)." (PMID 25303043, 2014). "The IL-6 cytokine levels were significantly higher in the aqueous humors of the VKH and BD patients compared with the AR cataract patients (P = 0.034 and P = 0.003, respectively), and the difference between the two disease groups was not significant (P = 0.921)." (PMID 25303043, 2014).
cataract (continued). "Additionally, the serum IL6 expression level in older diabetic patients with cataracts was significantly higher than that in older non-diabetic patients with cataracts and healthy individuals." (PMID 40598458, 2025). "So, we focused in the present study on evaluation of selected pro-inflammatory cytokines (IL-1β, IL-6, IL-8, IL-17A, and TNF-α), anti-inflammatory cytokines (IL-4, IL-10, and IL-13), and the IL-1 receptor antagonist (IL-1Ra) in the aqueous humor of FECD and/or cataract eyes." (PMID 38792359, 2024). "The expressions of interleukin-2 (IL-2), IL-4, IL-6, IL-10, IL-17A, and interferon-γ (IFN-γ) were analyzed in aqueous humor (AqH), phytohemagglutinin (PHA)-stimulated and non-PHA-stimulated cultures of peripheral blood mononuclear cells (PBMCs) from the three types of cataract patients." (PMID 25303043, 2014). "Serum levels of IL-6, IL-1β, CRP, and TNF-1α were higher in adult cataract patients than in non-cataract patients." (PMID 36830827, 2023).
diabetic cardiomyopathy (22 papers, 2011 to 2026). Diabetic cardiomyopathy is a disorder of the heart muscle in people with diabetes. "IL-6 plays a detrimental role due to its association in the initiation and development of inflammatory disease, diabetic cardiomyopathy, and lung dysfunction." (PMID 37122710, 2023). "In this study, we explored the role of interleukin-6 in the development of diabetic cardiomyopathy and the underlying mechanisms." (PMID 26972749, 2016). "For example, intramyocardial inflammation (including increased expression of IL-6 or TNF-α) contributed to diabetic cardiomyopathy." (PMID 35898716, 2022). "Cardiac expression of pro-inflammatory cytokines such as TNFα and IL6 often increases in settings of cardiac distress such as diabetic cardiomyopathy and acute MI, and this is necessary for tissue repair and healing." (PMID 31920673, 2019). "Another study compared the expression of inflammatory biomarkers like TNF alpha, IL-1beta, and IL-6 in diabetic cardiomyopathy mice in which MALAT1 was knockdown to a control group of diabetic cardiomyopathy mice where MALAT1 expression is intact." (PMID 29998127, 2018). "Remarkably, the deletion of IL-6 was also shown to be beneficial against diabetic cardiomyopathy through the attenuation of the cardiac fibrosis process." (PMID 30308936, 2018). "To further explore the role of IL-6 in interstitial fibrosis of diabetic cardiomyopathy, we firstly examined the influence of high glucose on the production of IL-6." (PMID 26972749, 2016). "Furthermore, deletion of IL-6 alleviates interstitial fibrosis also in experimental diabetic cardiomyopathy in IL-6−/− mice." (PMID 33833766, 2021). "Sullivan and collaborators hypothesize that alteration in expression in ghrelin receptor observed in diabetic cardiomyopathy could be a consequence of upregulation of inflammatory factors such as IL-1β, IL-6." (PMID 31375017, 2019). "Suppression of miR-29 upregulation may be one of the mechanisms responsible for the deleterious role of IL-6 in diabetic cardiomyopathy." (PMID 26972749, 2016). "However, the role of miR-29 in IL-6 induced collagen production and diabetic cardiomyopathy remains unknown." (PMID 26972749, 2016). "In the present study, diabetic cardiomyopathy is characterized by an decrease in the phosphorylation state of Akt and GSK-3β, which was associated with augmented cardiac inflammation as evidenced by increased NF-κB phosphorylation and TNF-α, IL-6 expression, as well as increased MPO activity." (PMID 21232147, 2011). "Mechanistically, inulin suppresses pro-inflammatory cytokines (e.g., IL-6, TNF-α), thereby attenuating systemic inflammation, preserving mitochondrial function, and inhibiting diabetic cardiomyopathy progression." (PMID 41601761, 2026). "IL-6, TNF-α and AGEs panel had AUC 0.924 for differentiating diabetic cardiomyopathy from DM-N (85% sensitivity and specificity)." (PMID 34046187, 2021). "Studies unveiled that inhibiting p38MAPK activity in diabetic cardiomyopathy mouse models effectively lowers the levels of inflammatory cytokines such as TNF-α, IL6, IL1-β, and TGF-β1 in myocardial tissue, thus improving the left ventricular function of DCM mice." (PMID 40373162, 2025). "In the context of diabetes cardiomyopathy, our analysis unveiled a substantial upregulation in the expression of TNF-alpha (p < 0.001), IL-6 (p < 0.001), and NF-κB (p < 0.001) within the heart tissues of the vehicle-treated rats compared to their respective control groups." (PMID 39496097, 2024).
esophageal adenocarcinoma (22 papers, 2009 to 2025). A malignant tumor with glandular differentiation arising predominantly from Barrett mucosa in the lower third of the esophagus. "In esophageal adenocarcinoma, IL-6 is secreted by cancer-associated fibroblasts (found in the tumor microenvironment), induces epithelial-to-mesenchymal transition of esophageal adenocarcinoma cell lines OE19 and OE33, and induces cell migration." (PMID 32595759, 2020). "Previous studies have found that higher circulating levels of certain metabolic and inflammatory biomarkers, including leptin, glucose, insulin, C-reactive protein, interleukin 6, and soluble tumor necrosis factor receptor 2, are associated with an increased risk of esophageal adenocarcinoma." (PMID 40917762, 2025). "In line with this, interleukin 6 (IL6) secreted by cancer-associated fibroblasts can induce EMT and drug resistance of esophageal adenocarcinoma." (PMID 37834284, 2023). "We further examined the effect of IL-33 on tumor-related cytokines and found that the mRNA expressions of IL-4 and IL-6 were significantly higher in the esophageal adenocarcinoma cells after IL-33 stimulation." (PMID 36110250, 2022). "We detected the tissue mRNA expression of IL-1β, IL-4, IL-6, and IL-10 in the esophageal adenocarcinoma rat model." (PMID 36110250, 2022). "IL-33 promotes the secretion of the tumor-promoting cytokine IL-6 by esophageal adenocarcinoma cells." (PMID 36110250, 2022). "Similarly, IL-33 promoted IL-6 secretion via ST2L in esophageal adenocarcinoma cells (OE19 and OE33)." (PMID 37834290, 2023). "Additionally, IL-6 acts as a stromal driver of therapeutic resistance by activating epithelial-to-mesenchymal transition in esophageal adenocarcinoma (EAC) which enhances the treatment." (PMID 36091805, 2022). "IL-6 activated EMT in esophageal adenocarcinoma cells and enhanced the migration ability of cells." (PMID 36110250, 2022). "For instance, CAF-secreted IL-6 induces STAT3 pathway activation, thus promoting epithelial-to-mesenchymal transition, growth, invasion, and chemoresistance of cancer cells in esophageal adenocarcinoma." (PMID 36635302, 2023). "IL-33 not only promoted the proliferation, migration, invasion and EMT of esophageal adenocarcinoma cells through ST2, but also promoted the secretion of IL-6." (PMID 36110250, 2022). "Other pathways, such as IL-6/JAK/STAT signaling, were similarly shown to mediate CRT resistance in a subset of esophageal adenocarcinomas." (PMID 34638639, 2021). "Exposure of Barrett’s and esophageal adenocarcinoma cells to acidic bile salts activated EGFR-Stat3 signaling (EGFR-STAT3 protein complex) and induced the expression of Stat3 target genes (IL-6, IL-17A, BCL-xL, Survivin, and c-MYC)." (PMID 34884765, 2021). "In esophageal adenocarcinoma, although IL-6 serum levels did not correlate with patients' outcome, the expression of ADAM-12, a surrogate marker for IL-6-producing CAFs, predicted poor prognosis after neoadjuvant chemoradiation." (PMID 33553157, 2020).